IGLV7-46 (immunoglobulin lambda variable 7-46)
Description:
V region of the variable domain of immunoglobulin light chains that participates in the antigen recognition. Immunoglobulins, also known as antibodies, are membrane-bound or secreted glycoproteins produced by B lymphocytes. In the recognition phase of humoral immunity, the membrane-bound immunoglobulins serve as receptors which, upon binding of a specific antigen, trigger the clonal expansion and differentiation of B lymphocytes into immunoglobulins-secreting plasma cells. Secreted immunoglobulins mediate the effector phase of humoral immunity, which results in the elimination of bound antigens. The antigen binding site is formed by the variable domain of one heavy chain, together with that of its associated light chain. Thus, each immunoglobulin has two antigen binding sites with remarkable affinity for a particular antigen. The variable domains are assembled by a process called V-(D)-J rearrangement and can then be subjected to somatic hypermutations which, after exposure to antigen and selection, allow affinity maturation for a particular antigen.
Synonyms: IGLV746; V3-3
Gene: Immunoglobulin variable (V) gene on chromosome 22 (22,369,614 to 22,370,087, forward strand). Ensembl gene ENSG00000211649.
Subcellular location: Secreted; Cell membrane
Gene Ontology:
Biological process: immune response
Cellular component: extracellular region; immunoglobulin complex; plasma membrane
Homologues: Paralogues in human: IGLV7-43 (91% identical), IGLV8-61 (62% identical), IGLV1-40 (50% identical), IGLV3-10 (50% identical), IGLV3-25 (49% identical), IGLV5-52 (49% identical), IGLV2-18 (48% identical), IGLV5-37 (48% identical), IGLV5-45 (48% identical), IGLV1-47 (47% identical), IGLV11-55 (47% identical), IGLV3-1 (47% identical), and 81 more.
Diseases named in the same sentence as IGLV7-46 in open-access papers:
IGLV7-46 is named in the same sentence as 2 diseases in open-access papers, as found by Europe PMC text mining. Sharing a sentence is not in itself a finding about the gene and the disease.
IGLV7-46 shares sentences with these, for which no sentence is quoted: polycystic kidney disease (1 paper); tumor (1).